ENSG00000288908 (novel transcript)
Gene: Long non-coding RNA gene on chromosome X (48,958,643 to 48,959,773, forward strand). Ensembl gene ENSG00000288908.
Gene Ontology:
Molecular function: U4 snRNA binding
Biological process: formation of quadruple SL/U4/U5/U6 snRNP; spliceosomal tri-snRNP complex assembly
Cellular component: U4/U6 x U5 tri-snRNP complex; U6 snRNP